NRP1 (neuropilin 1)
Diseases named in the same sentence as NRP1 in open-access papers (continued):
Sharing a sentence is not in itself a finding about the gene and the disease.
cholangiocarcinoma (8 papers, 2019 to 2024). A carcinoma that arises from the intrahepatic biliary tree (intrahepatic cholangiocarcinoma) or from the junction, or adjacent to the junction, of the right and left hepatic ducts (hilar cholangiocarcinoma). "Two recently published reports already established that chemotherapy induced PlGF expression, which activated Nrp1-expressing cancer-associated fibroblasts, and thereby promoted desmoplasia and tissue stiffness in PDAC and cholangiocarcinoma." (PMID 38816706, 2024). "lncRNA titin-antisense RNA1 is overexpressed in cholangiocarcinoma and it can sponge miR-320a to regulate neuropilin-1 expression." (PMID 34721048, 2021). "TTN-AS1 promoted the proliferation and migration of cholangiocarcinoma cells via the miR-320a/ neuropilin-1 axis." (PMID 32801339, 2020). "Neuropilin-1 regulated by miR-320a participates in the progression of cholangiocarcinoma by serving as a co-receptor that activates multiple signaling pathways." (PMID 32801339, 2020). "We have recently reported that NRP-1 is overexpressed in gastric cancer and cholangiocarcinoma, and contributes to their clinicopathology, cell growth and metastasis." (PMID 31572065, 2019). "We have recently demonstrated that NRP-1 regulated by miR-320 contributes to the growth and metastasis of cholangiocarcinoma cells." (PMID 31572065, 2019). "In conclusion, the present results demonstrate that lncRNA TTA-AS1 is a sponging ceRNA for miR-320a, which in turn downregulates neuropilin-1 in cholangiocarcinoma cells, indicating these three molecules represent potential biomarkers and therapeutic targets in the management of cholangiocarcinoma." (PMID 32801339, 2020).
colon adenocarcinoma (8 papers, 2007 to 2023). "Inhibition of NRP1 expression in WiD human colon adenocarcinoma cells induced by RNA interference decreases cell migration." (PMID 37894289, 2023). "The role of NRP-1 in migration was also demonstrated for a human colon adenocarcinoma cell line WiDR, which showed a significant drop in migratory activity after transfection with NRP-1 siRNA." (PMID 17912247, 2007). "Interestingly, co-expression of ACE2 and NRP1 on a human colon adenocarcinoma cell line (Caco-2) led to an increase in infectivity when compared to that observed with cells that only expressed the ACE2 receptor." (PMID 36768649, 2023). "Measuring NRP1 expression by immunohistochemistry and in situ hybridization shows ubiquitous expression in colon adenocarcinoma tumors, and reverse transcriptase-polymerase chain reaction analysis (RT-PCR) shows NRP1 mRNA expression in colon adenocarcinoma cell lines." (PMID 37894289, 2023). "Meanwhile, the mRNA expression of NRP1 was significantly down-regulated in five cancer types, including breast invasive carcinoma (BRCA), lung squamous cell carcinoma (LUSC), uterine corpus endometrial carcinoma (UCEC), kidney chromophobe (KICH), and colon adenocarcinoma (COAD)." (PMID 36338984, 2022).
lymphoma (8 papers, 2007 to 2025). A malignant (clonal) proliferation of B- lymphocytes or T- lymphocytes which involves the lymph nodes, bone marrow and/or extranodal sites. "In a study utilizing the λ-MYC mouse model of BL, tumor-promoting Tregs were found to express canonical nTregs markers Helios and NRP-1 and recognized antigens expressed by lymphoma cells." (PMID 35979372, 2022). "Furthermore, NRP1 is identified as an EBV entry factor, its overexpression enhances EBV infection in nasopharyngeal epithelial cells, and highly expressed NRP1 could be consider as an undesirable independent prognostic factor in EBV-associated lymphomas." (PMID 34249735, 2021). "Lymphoma-derived Tregs limited responder cell proliferation and IFN-γ production more than WT-derived Tregs, and this suppressive ability was dependent on surface NRP-1, PD-L1 and soluble IL-10." (PMID 35979372, 2022).
oral cancer (8 papers, 2012 to 2022). "The expression of ACE-2, and NRP-1 in our study was higher in healthy pulp tissue than in periapical oral lesions, which is different than the results reported in the case of oral cancer, another oral pathological condition." (PMID 34749700, 2021). "Tumorigenesis of oral cancer is stimulated by the capability of miR-320 to target the 3′-UTR of Neuropilin 1 (NRP1)." (PMID 34946938, 2021). "ACE-2 and NRP-1 gene expression was reported at higher levels in oral cancer tissues." (PMID 34749700, 2021). "Further investigation of the role of NRP1 in tumorigenesis may help identify novel targets for the prevention and therapy of oral cancers." (PMID 24999732, 2014). "The increased expression of neuropilin-1 (NRP1) contributes to the migration of cells and invasion of oral cancer cells." (PMID 36146567, 2022). "In this study, we focused on the most common type of oral cancer, tongue squamous cell carcinoma, and examined the expression of SEMA3A and NRP1." (PMID 22926477, 2012).
pancreatic adenocarcinoma (8 papers, 2012 to 2025). "NRP1 is upregulated in T regulatory cells from patients with pancreatic adenocarcinoma and colorectal cancer (CRC) metastasis to the liver." (PMID 37894289, 2023). "A recent report has shown that silencing Nrp1 diminished TGFβ signaling in pancreatic adenocarcinoma cells, but also inhibited TGFβ1-induced Smad2 phosphorylation in endothelial cells (HUVECs) and blocked endothelial to mesenchymal transition and fibrosis." (PMID 28938007, 2017). "For example, a high expression of NRP1 is significantly correlated with angiogenesis, an advanced tumor–node–metastasis stage, p T stage, node invasion, and poor postoperative overall survival in patients with pancreatic adenocarcinoma." (PMID 37894289, 2023). "By contrast, pancreatic adenocarcinoma cells showed immunoreactivity toward most members of SEMA3 and Plexin family, and NRP1." (PMID 23251334, 2012).
pulmonary fibrosis (8 papers, 2020 to 2026). Chronic progressive interstitial lung disorder characterized by the replacement of the lung tissue by connective tissue, leading to progressive dyspnea, respiratory failure, or right heart failure. "SEMA3B functions as an inhibitor of transforming growth factor-β-driven fibroblast activation and reduced levels of SEMA3B and its receptor, neuropilin 1, are associated with decreased lung function in idiopathic pulmonary fibrosis." (PMID 38646784, 2024). "The decreased expression of SEMA3B is not limited to IPF, we observed reduced expression of SEMA3B and NRP1 in two alternative mouse models of pulmonary fibrosis." (PMID 38646784, 2024). "Deficiency in NRP1 downregulates ST2, weakens ILC2 function, and alleviates pulmonary fibrosis." (PMID 39301028, 2024). "Therefore, it is possible that these profibrotic factors can interfere with the binding of SEMA3B to NRP1 during pulmonary fibrosis development." (PMID 38646784, 2024). "The downregulation of SEMA3B and NRP1 transcripts was validated in the lung tissues of patients with IPF, and two alternative mouse models of pulmonary fibrosis." (PMID 38646784, 2024). "To determine the role of the SEMA3B-NRP1 axis in preclinical mouse models of pulmonary fibrosis, we quantified the expression of SEMA3B and NRP1 in the lungs of mice with severe fibrotic lung disease in two murine models of pulmonary fibrosis, bleomycin (BLM)-induced, and TGFα-induced lung fibrosis." (PMID 38646784, 2024). "This could explain that in contrast to NRP1 inhibition, no significant hematologic impairment has been observed in phase III clinical trials targeting NRP2 in pulmonary fibrosis (NCT03824392, NCT04412668)." (PMID 38792002, 2024).
type 2 diabetes (8 papers, 2014 to 2025). "The Renin-Angiotensin System (RAS) is activated in type 2 diabetes (T2D); therefore, the aim of this study was to determine if hypoglycaemia-induced stress in T2D would potentiate serum NRP1(sNRP1) levels, reflecting an increased risk for SARS-CoV-2 infection." (PMID 34248841, 2021). "Inhibition of Neuropilin 1 (NRP1), which is expressed in pancreatic tissue, has been reported to improve glucose tolerance in type 2 diabetes as well as in glucose intolerance after SARS-CoV2 infection." (PMID 39861420, 2025). "Several lines of evidence demonstrate a reduced NRP-1 expression in glycated-BSA cultured differentiated podocytes as well as in glomeruli from db/db mice (a model of type 2 Diabetes) and in diabetic patients diagnosed with DN." (PMID 26239560, 2015). "One hundred ns molecular dynamics simulations (MD) of drug-NRP1 complexes showed that thrombopoietin receptor agonist eltrombopag, migraine drug ergotamine, drugs for type 2 diabetes sitagliptin and glimepiride, and antiandrogen dutasteride can stably interact with NRP1." (PMID 34803446, 2021).
Arthritis (7 papers, 2012 to 2024). Inflammation of a joint. "A peptide interfering with VEGF‐A165 binding to NRP‐1 suppresses angiogenesis in experimental arthritis." (PMID 34252269, 2022). "Statistical analysis revealed a significant interaction between time-of-day and disease, confirming that the effect of arthritis on NRP1 expression was greater at ZT18." (PMID 32245954, 2020). "This study demonstrates that VD treatment significantly delayed CIA disease onset and decreased the severity of arthritis by downregulating inflammatory Th17 cells while increasing CD4+Foxp3+Nrp-1+ cells." (PMID 30792721, 2019). "The role of NRP-1 in experimental arthritis has been studied before." (PMID 22817681, 2012). "To further analyse its role in arthritis-induced angiogenesis, we investigated whether NRP-1 function is required for the induction of endothelial cell migration by arthritic paw homogenates applying a neutralising antibody that specifically blocks the binding of VEGF121 and VEGF164 to NRP-1." (PMID 22817681, 2012).
asthma (7 papers, 2013 to 2026). "Expression of both, NRP1 and its another ligand, Sema3A, was found to be upregulated in sputum of asthmatic patients and in BAL and lung homogenates of mice with OVA-induced experimental asthma suggesting NRP1 and its ligands play a pathologic role in allergic asthma." (PMID 34961486, 2021).
astrocytoma (7 papers, 2003 to 2023). "In astrocytoma cell lines and specimens, the expression pattern of NRP1 is closely associated with more malignant tumors." (PMID 37894289, 2023). "NRP1 RNA levels are also significantly higher in GBM compared to grade II/III astrocytomas or grade III oligodendrogliomas." (PMID 28938007, 2017). "Other investigators have shown that EGF increases NRP-1 expression in human malignant astrocytoma cell lines and that the expression of NRP-1 mRNA peaks at 4 h and returns to basal levels 8 h after EGF treatment." (PMID 12618892, 2003). "Increased NRP1 expression is observed in a transgenic mouse astrocytoma model of astrocytomas." (PMID 37894289, 2023). "Mitogens relevant for astrocytoma proliferation, such as EGF and p21-Ras, induce NRP1 expression." (PMID 37894289, 2023). "Cluster analysis within astrocytoma samples listed only VEGF and NRP1 within one complex." (PMID 31952211, 2020). "Studies in an astrocytoma cell line showed that activation of p21-Ras induces not only VEGF but also NRP-1 expression." (PMID 12618892, 2003).
autoimmune disease (7 papers, 2017 to 2025). A disorder resulting from loss of function or tissue destruction of an organ or multiple organs, arising from humoral or cellular immune responses of the individual to their own tissue constituents. "Overall, it appears that intrinsically self‐reactive Th cells in systemic autoimmune disease may have shared phenotypes with Treg cells, with NRP1+ conventional Th cells highly associated with autoimmune disease induction in NR4A2‐dependent manner." (PMID 36069030, 2022). "As Foxp3− Th cells expressing both NRP1 and PD‐1 were associated with autoimmune disease, we next tested whether or not NRP1/PD‐1‐expressing conventional Th cells were directly pathogenic." (PMID 36069030, 2022). "Although beyond the scope of the current studies, these observations suggest that the combined effects of NRP1 and NRP2 are necessary for Treg function which is critical for long-term transplant survival, the prevention of autoimmune disease, and/or tumor immunity." (PMID 40590224, 2025). "Redundancy also explains why deletion of the NRP1 gene alone on Foxp3+ Tregs does not result in autoimmune disease." (PMID 40590224, 2025). "Unlike in systemic autoimmune disease, these NRP1+ Th cells did not express PD‐1 (Fig EV4I), suggesting NRP1 expression in autoimmune disease is not only limited to Tph and Tfh cells." (PMID 36069030, 2022).
heart failure (7 papers, 2014 to 2026). Inability of the heart to pump blood at an adequate rate to meet tissue metabolic requirements. "A knockout mouse study shows that the knockout of NRP-1 in cardiomyocytes and vascular smooth muscle cells leads to the development of cardiomyopathy and causes the mice to be prone to heart failure after MI." (PMID 39457610, 2024). "Furthermore, we extended the analysis by showing that Nrp1 conditional mutants were more prone to develop cardiac fibrosis in a mouse model of heart failure." (PMID 41432227, 2026).
lupus nephritis (7 papers, 2016 to 2024). Glomerulonephritis in the context of systemic lupus erythematosus. "Urinary NRP-1 has been proposed as a biomarker for lupus nephritis due to its high expression in mesangial cells." (PMID 38791476, 2024). "This is the first study showing urinary NRP-1 both at a protein and gene expression level to be significantly increased in patients with active lupus nephritis." (PMID 31533337, 2019). "Thus, our findings indicate that kidney and urine NRP-1 levels are closely related to recovery from lupus nephritis." (PMID 39518917, 2024). "In conclusion, our results demonstrate that urinary and renal NRP-1 levels at the time of renal flare may serve as a novel prognostic biomarker for prediction of clinical response in lupus nephritis." (PMID 31533337, 2019). "It was reported that overexpression of NRP-1 could damage kidneys in lupus nephritis." (PMID 35884827, 2022). "In the non-treated group, serum NRP-1 levels remained consistently higher compared to in urine throughout the progression of lupus nephritis." (PMID 39518917, 2024). "The expression of Sema3A and its receptor, neuropilin-1, was decreased in peripheral blood of mononuclear cells (PBMC) in patients with SLE, while the expression of Sema3A was strong in the tubules in lupus glomerulonephritis." (PMID 36012289, 2022). "Little is known about the involvement of NRP-1 in SLE, and its role in lupus nephritis." (PMID 31533337, 2019).
nasopharyngeal carcinoma (7 papers, 2013 to 2023). A carcinoma arising from the nasopharyngeal epithelium. "EBV drives NPC metastasis through EBV-encoded LMP1-mediated metabolic reprogramming via activation of IGF1-mTORC2 signaling and nuclear acetylation of the Snail promoter by PDHE1α, LMP1 upregulates calreticulin to induce EMT via the TGF-β/Smad3/NRP1 pathway in nasopharyngeal carcinoma cells." (PMID 35388172, 2022).
stomach cancer (7 papers, 2016 to 2023). "Moreover, NRP1 inhibition hinders gastric tumor growth and lung metastasis by reducing cell proliferation and tumor angiogenesis." (PMID 37894289, 2023). "Expression of NRP1 in both vessels and tumor cells was detected in 11/17 cancer types, but in most cases only in a very limited number of samples, with the exception of pancreatic and gastric tumors." (PMID 30027561, 2018). "Furthermore, NRP1 knockdown by a shRNA lentivirus inhibits the growth of BGC823 gastric tumors." (PMID 37894289, 2023).
Cerebral ischemia (6 papers, 2021 to 2025). Restriction of arterial blood supply to the brain associated with insufficient oxygenation to support the metabolic requirements of the tissue. "However, it remains unraveled whether this very signaling pathway is implicated in the NRP-1-promoted mitochondrial structural repair and functional recovery, thus alleviating the symptoms of neurological deficit in rats after cerebral ischemia." (PMID 37138283, 2023). "However, it remains obscure whether NRP-1 can promote mitochondrial structural repair and functional recovery after cerebral ischemia and the underlying molecular mechanisms remains unexplored." (PMID 37138283, 2023). "NRP1 is a direct target of the nuclear transcription factor E2F1 in regulating axonal damage and neuronal death associated with cerebral ischemia." (PMID 37894289, 2023). "In in vitro and in vivo rat models of cerebral ischemia, a sharp increase in NRP1 expression is observed in the neural tissue." (PMID 37894289, 2023). "Both in vitro and in vivo models of cerebral ischemia/reperfusion (I/R) injury presented a sharp increase in NRP-1 expression." (PMID 37138283, 2023). "Another study indicated that the nuclear transcription factor E2F1 plays an important role in modulating neuronal death in response to cerebral ischemia by enhancing the NRP1 level via binding NRP1 promoter sequence." (PMID 35350431, 2022). "Among them, the target gene neuropilin-1 (NRP1) is a direct target of the transcription factor E2F1 in cerebral ischemia-induced neuronal death." (PMID 33675584, 2021). "Among them, the target gene neuropilin-1 (NRP1) was a direct target of the transcription factor E2F1 in cerebral ischemia-induced neuronal death." (PMID 33675584, 2021). "NRP1 has been shown to play an important role in axonal growth and neuronal death induced by cerebral ischemia." (PMID 33675584, 2021). "Our study demonstrates that THRIL can aggravate cerebral ischemia-reperfusion injury by competitively binding to miR-24-3p to promote the upregulation of NRP1 expression and further promote the activation of the NF-κB p65 signaling pathway." (PMID 33675584, 2021). "In conclusion, THRIL could aggravate cerebral ischemia-reperfusion injury by competitively binding to miR-24-3p to promote the upregulation of NRP1 and further promote the activation of the NF-κB p65 signaling pathway." (PMID 33675584, 2021). "However, whether NRP-1 can repair mitochondrial structure and promote functional recovery after cerebral ischemia is still unknown." (PMID 37138283, 2023). "Furthermore, cerebral ischemia induced by occlusion led to CRMP4 and Nrp1 recruitment to lipid rafts, which hints that these molecules play a role in mediating signal transduction in response to neuronal damage triggered by ischemia-reperfusion." (PMID 34860155, 2021).
clear cell renal cell carcinoma (6 papers, 2016 to 2025). "In clear cell renal cell carcinoma (ccRCC) patients we find that NRP1+ T cells often express PD-1 and are trapped in SEMA3A-rich areas." (PMID 38609390, 2024). "The kidney clear cell carcinoma (KIRC) dataset showed approximately 10‐ to 50‐fold elevated levels of NRP1 mRNA, as compared to normal kidney tissue." (PMID 31880322, 2020). "To demonstrate binding and uptake, we conjugated biotinylated miRNA to streptavidin-coated fluorescent microparticles and incubated them with cultured NRP1-expressing cells of the ACHN renal clear cell carcinoma cell line." (PMID 27486976, 2016). "Single-cell RNA sequencing (scRNA-seq) analyses were performed on tumours from clear cell Renal Cell Carcinoma (ccRCC) and skin cutaneous melanoma (SKCM) which exhibit the highest expressions of NRP1 and NRP2, respectively." (PMID 40134439, 2025). "Furthermore, analysis of renal clear cell carcinoma showed that GNB1 was correlated with WASP family member 2 (WASF2), Neuropilin-1 (NRP1) and huntingtin interacting protein 1 (HIP1) of the vascular endothelial growth factor (VEGF) signaling pathway." (PMID 35193469, 2022).